CXCL1 (C-X-C motif chemokine ligand 1)
Diseases named in the same sentence as CXCL1 in open-access papers (continued):
Sharing a sentence is not in itself a finding about the gene and the disease.
infection (continued). "The expression levels of interleukin (IL)-6 and CXCL1/CXCL2 in MZ B cells increased significantly in mice at 3–4 h after infection with S. aureus, then decreased at 24 h post-infection." (PMID 34040603, 2021). "If the infection persists, the infected cells can recruit innate immune cells such as neutrophils and monocytes in the blood by releasing chemokines such as C-X-C motif chemokine ligand 1 (CXCL1) and C-C motif ligand 8 (CCL8)." (PMID 34335278, 2021). "Mincle-/- MΦ infected with live bacteria produced significantly less Cxcl1 and Ccl2 early in infection than WT cells, indicating this receptor plays a role in propagating inflammation." (PMID 34320039, 2021). "After 1 day of infection, the oral tissues of the gefitinib-treated mice contained significantly less CXCL1/KC, CCL20, IL-1α, IL-1β, IL-17A, and the host defense peptide S100A8 than control mice." (PMID 33471869, 2021). "CXCR2 is the receptor for CXCL1, which is produced in the respiratory tract during infection with B. pertussis in response to IL-17." (PMID 33976385, 2021). "Neutrophil recruitment in the blood and at infection sites is orchestrated by chemotactic cytokines/chemokines, including GM-CSF, CXCL1/2, TNF-α, and IL-6." (PMID 34899755, 2021). "The chemokine CXCL1 recruits and activates neutrophils to the site of infection, and it is essential for the expression of pro-inflammatory mediators, activation of NF-kB, and MAPKs." (PMID 34575163, 2021). "Moreover, infection of the Colon Chips with the pathogenic bacterium, Salmonella typhimurium, resulted in epithelial detachment, decreased tight junction staining, and increased release of chemokines (CXCL1, CXCL2, and CCL20) that closely mimicked changes previously seen in mice." (PMID 33777849, 2021). "In response to methicillin-resistant Staphylococcus aureus infection, treatment with CGRP inhibited TNF-α and CXCL1 by lung cells and the levels of this neuropeptide significantly increased after infection." (PMID 34012447, 2021). "In influenza A virus (IAV) infected mice, NLRP12 exacerbated the pathogenesis of infection by facilitating massive neutrophil chemotaxis via promoting CXCL1 expression." (PMID 34956178, 2021). "In control animals, we noted a significant increase in proinflammatory cytokines (IL-1α, IL-1β, IL-6, and TNF-α), and chemokines (RANTES/CCL5 and CXCL1) coupled with the surge of G-CSF in response to infection." (PMID 33514747, 2021). "Our RT-qPCR results confirmed that the Cxcl1 and Cxcl2 mRNA levels were increased at 4 h post-infection but were decreased at 24 h post-infection." (PMID 34040603, 2021). "A quantitative analysis performed by using MetaMorph software indicated that depletion of CXCL1/CXCL2 before infection prevents neutrophil recruitment to the MZ." (PMID 34040603, 2021). "Our findings suggest that IL-17 mediates neutrophil recruitment through induction of chemokines, especially CXCL1, in the respiratory tract soon after infection with B. pertussis." (PMID 33976385, 2021). "Nonetheless, the enhanced CXCL1 release early after infection was accompanied by a faster influx of neutrophils into the alveolar compartment, which is a likely explanation for a subsequent accelerated bacterial clearance." (PMID 33793661, 2021). "Significantly higher secretion of CXCL1/KC, IL-1β, and IL-6 in the mouse lung upon infection with A. flavus conidia also suggest that A. flavus conidia are more efficiently cleared by the host as compared to A. fumigatus conidia." (PMID 33718288, 2021). "Under normal conditions, CXCL1 levels are negligible, however, they increase substantially during active infections in the lungs." (PMID 34737734, 2021). "We found an increased total number of cells in the airways, including neutrophils, DCs, and T cells, as well as enhanced expression of Cxcl1, S100a8, and S100a9 after RV‐A1b infection in Mir146a/b−/‐ mice compared to wt mice." (PMID 34185416, 2021).
infection (continued). "L. rhamnosus L8020 treatment significantly reduced the expression levels of Dectin-2 and CCL2, and tended to reduce the expression levels of TLR2 and CXCL1/KC, following infection by C. albicans GDH18." (PMID 33919079, 2021). "Mice lacking IL-17 failed to clear the bacteria from the nasal mucosae following infection with B. pertussis and these mice had defective production of CXCL1 and recruitment of Siglec-F+ neutrophils." (PMID 33976385, 2021). "CXCL-1 is involved in the mobilization of leukocyte infiltrates, particularly neutrophils, toward the infection site, and is an important mediator in regulating systemic C. albicans infection locally." (PMID 33396406, 2020). "To further study the effect of PKK depletion on lung inflammation after infection, we measured the levels of cytokines (TNFα, IL‐1β, IL‐6) and chemokines (CXCL1, CXCL2) in lung homogenates." (PMID 31595971, 2020). "The level of CXCL1 mRNA in the lungs before infection was higher in klotho KO mice than in klotho WT mice." (PMID 33329595, 2020). "Of these 7 cytokines/chemokines, only 4 were expressed in wild type at relatively low concentrations, while 3 (CCL20, CCL17, CXCL1) appeared to be uniquely expressed in Nlrx1-/- mice at this early stage of infection." (PMID 32956405, 2020). "The blood collected after infection in mice was also used to investigate levels of the proinflammatory cytokine CXCL1." (PMID 32295520, 2020). "Levels of bacteria and the proinflammatory cytokine CXCL1 were determined in blood collected 3 h and 24 h post-infection." (PMID 32295520, 2020). "We also found a direct correlation in both PTB in mice with ascending infection and significant relationship between UP presence and increased TNFα, IL-1β, CXCL-1 and CXCL-2 cytokine expression in foetal membranes, placenta and the myometrium." (PMID 31924800, 2020). "CXCL2 (MIP‐2) and CXCL1 (KC), which are responsible for the infiltration of neutrophils and monocytes, were suppressed at the beginning of infection (6 h), whereas inhibition of CCL2 (MCP‐1), TNF‐α, IL‐6, IL‐1β and IL‐17A appeared after 24 h." (PMID 33014369, 2020). "For this, we measured the expression levels of lung Cxcl1, Cxcl2 and Cxcl5 during infection with low or high doses of Mtb." (PMID 32203062, 2020). "Here, we show that depleting CXCL1 reduces the liver damage during infection, a phenomenon paralleled by reduced frequency of Ly6Chi monocytes." (PMID 32651360, 2020). "These factors are critical for virulence and, during infection, induce secretion of interleukin-6, CXCl1, and CXCL2, assist with bacterial dissemination to the spleen, and stabilize hypoxia inducible factor-1a (HIF-1a)." (PMID 32390954, 2020). "We found that both MLE-12 cells and polarized mouse tracheal epithelial cells (mTECs) were susceptible to infection with Influenza A and released proinflammatory cytokines, including CCL2, CCL5, CXCL1, and CXCL10, in response to replicating virus." (PMID 33374950, 2020). "Chemokines produced during the course of RSV infection have been linked to disease severity, including CXCL1, CCL2 and CCL5, either in murine models of infection or in patients." (PMID 32107411, 2020). "Mechanistically, chronic ethanol consumption impairs the normal neutrophil migration to the site of infection via release of high levels of circulating chemokine CXCL1 after infection, followed by downregulation of its receptor 2 (CXCR2)." (PMID 32701055, 2020). "In support of this interpretation is the fact that FABP4 facilitates the interaction between Mɸ and neutrophils through the regulation of CXCL1, a chemokine secreted by Mɸ to recruit neutrophils to the site of infection." (PMID 31931795, 2020). "It was reported that IL-17 promoted the chemokine (e.g., CXCL1, 2, and 5) production from the epithelial cells mediated by IL-17R, thus promoting neutrophil recruitment to infection sites." (PMID 32718009, 2020).
infection (continued). "Some studies have indicated that MHV-JHM can infect oligodendrocytes, astrocytes and microglia, which are responsible for secreting cytokines and chemokines such as IFN-I and C-X-C motif chemokine 1 (CXCL1) following infection." (PMID 31652591, 2019). "In contrast, at 48 and 72 h p.i. it was found that the expression of RANTES, IL-12p40 and CXCL1 were upregulated indicating an initiation of the host response to infection." (PMID 31546628, 2019). "This also extends to proteins involved in cellular recruitment, specifically CXCL1/KC, a chemokine involved in neutrophil attraction, which is expressed early and at high levels during a rampant B. pseudomallei infection." (PMID 31546628, 2019). "After four hours of infection, we collected cells and isolated RNA for RT-qPCR analysis to quantify IL-8 and CXCL-1 transcripts." (PMID 31181121, 2019). "Under LD conditions, mice infected during the day had significantly higher levels of CXCL-1 during the first week of infection compared to mice infected at ZT15 (p < 0.01)." (PMID 31388084, 2019). "While all the cytokine levels returned to basal levels in wild-type mice by 2 days post-infection, Foxo3a mice showed sustained expression of IL-1β, CXCl-1, and TNF-α up to 3 days." (PMID 31796819, 2019). "TNFɑ induces downstream targets (e.g. neutrophil chemokines such as CXCL1) that stimulate neutrophil recruitment to the site of infection, supporting our observations of decreased neutrophil recruitment to the bladder and pyuria in TNFɑ-depleted Resolved mice." (PMID 31429405, 2019). "For instance, mice infected during the early rest period had significantly higher levels of CXCL-1 in the first week of infection compared to mice infected during the early active period." (PMID 31388084, 2019). "In contrast, Il1r1-/- mice display significantly higher levels of GM-CSF and CXCL1 at day 5 post-infection when compared to WT mice, prior to the decrease in bacterial burdens that occurs between days 5 and 10 post-infection." (PMID 30978245, 2019). "Compared to uninfected cecal tissues, infection led to the significant upregulation (10- to 500-fold) in transcription of the neutrophil-attracting chemokines Cxcl1 and Cxcl2." (PMID 31848276, 2019). "Upon infection with L. major, CXCL1 is produced locally and plays an important role in the recruitment of neutrophils to the site of infection." (PMID 31260451, 2019). "In the immunocompetent mice, the Chr6ABB strain induced significantly less CCL3, CXCL1 (KC), IL-1β, IL-17A, and the p19 subunit of IL-23 in the oral tissues relative to the progenitor strain after 1 day of infection." (PMID 31091232, 2019). "Consistent with increased cellular recruitment, evaluation of lung homogenates showed an overall increase in TNF, IL-1β, IL-6, IL-17 and KC (CXCL1) in Mtb-LT infected mice at four weeks following infection compared with Mtb-HT infected mice." (PMID 30840702, 2019). "In sera, only the peak concentrations of Cxcl1 (8 h), Ccl2 (8 h), Ccl3 (8 h), IL-1β (4 h), and IL-6 (4–8 h after infection) were significantly elevated in ExoY-infected mice as compared to ExoYK81M-infected mice." (PMID 29734720, 2018). "In fact, several of the cytokines seen here are the same neutrophil chemokines (Cxcl5, Ccl4, Cxcl1) and T-cell chemokines (Cccl5, Cxcl10, Ccl17) that were highlighted in the infection effect analysis." (PMID 30134832, 2018). "At 2 h post infection (p.i.), enhanced accumulation of mRNAs for Cxcl1, Cxcl2, Cxcl3, and Cxcl5, as well as Ccl3 and Ccl4, was evident (determined as differentially expressed using a 5% FDR)." (PMID 29636754, 2018). "CXCL-1, also called keratinocyte-derived cytokine (KC), is a predominant chemokine produced in glial cells upon infection with Theiler's murine encephalomyelitis virus (TMEV)." (PMID 29410948, 2018). "Infected, solvent-treated mice showed an infection-time-dependent increase in CXCL1, CXCL2 and CXCL5." (PMID 30382866, 2018).
infection (continued). "Meanwhile, the mRNA expression of Ifnα, Ifnβ, Ifnγ, Tnfα, and selective chemokines (Cxcl1, Cxcl2, and Ccl5) by leukocytes was lower in the blood of Ddx25-Tg mice on day 1 post-infection." (PMID 28824886, 2017). "This is consistent with the data demonstrating that MyD88/TLR signaling is necessary for CXCL1 expression, which attracts neutrophils to the site of infection necessary for bacterial clearance." (PMID 28796783, 2017). "The recruitment of neutrophils into infection sites is mainly mediated by CXCR2 functioning with CXCL1 and CXCL2." (PMID 28878779, 2017). "This translated into an improved bacterial clearance with reduced systemic dissemination of pneumococci, lower pulmonary CXCL1 levels, and less severe lung infiltrates in Il7rCreRorasg/fl mice 48 hr after infection." (PMID 28228256, 2017). "In accordance with the reduced bacterial burden, we found decreased CXCL1 levels, lower numbers of infiltrating monocytes, and less pronounced lung infiltrates at 48 hr post-infection in Il13−/− as compared to WT animals." (PMID 28228256, 2017). "In contrast, only a few immunity-related mRNAs encoding chemokines (Cxcl10, Cxcl1, Ccl2) and the invariant chain (CD74) were up-regulated in multiple host cell types after infection." (PMID 28775382, 2017). "Of note, H. polygyrus infection promoted a long term up-regulation of IL-6 and CXCL1 expression in naïve mice which was still detectable 10 weeks after initial infection." (PMID 28938014, 2017). "Infection of Il7rCreRorasg/fl mice with S. pneumoniae resulted in increased neutrophil influx and higher lung CXCL1 levels 6 hr post-infection." (PMID 28228256, 2017). "Focusing on CXCL1 expression, at 6 h post-infection a 4.5-fold increase in CXCL1 expression was observed for SM-HPBCs at the MOI 10:1 as well as a 12.3-fold increase for MOI 30:1." (PMID 27446812, 2016). "The chemokines Ccl2, Ccl7 and Cxcl1 were also expressed at higher levels in cPLA2α−/− compared to cPLA2α+/+mice 12 h after infection, but at 24 h they decreased to a greater extent in cPLA2α−/− than cPLA2α+/+mice." (PMID 27501951, 2016). "At 24 h, tonB K. pneumoniae infection also caused levels of induction of IL-6, CXCL1, CXCL2, IL-1β, and MIP-3α secretion that were comparable to those seen after 48 h of infection with WT K. pneumoniae." (PMID 27624128, 2016). "Only infection with the tonB mutant was sufficient to induce more secretion of IL-6, CXCL1, or CXCL2 than infection with the entB ybtS tonB (siderophore-negative) mutant, indicating that all three siderophores are required for secretion of these cytokines." (PMID 27624128, 2016). "The same pattern was observed for CXCL10 (age: p<0.001, infection: p=0.609, infection*time: p =0.684), CXCL1 (age: p<0.001, infection: p=0.865, infection*time: p =0.121), and CCL2 (age: p<0.001, infection: p=0.921, infection*time: p =0.263)." (PMID 26856410, 2016). "CXCL1 levels are negligible under basal conditions but increase significantly during active infection." (PMID 27625115, 2016). "Clinical studies and animal models have shown that the chemokine CXCL1 plays dual roles in the host immune response by recruiting and activating neutrophils to combat infection." (PMID 27625115, 2016). "The levels of IFNγ,IL-12/IL-23 p40, IL-1β, CXCL1/KC as well as the expression of CXCR2 wereincreased in the lung of M-TNFR1 KO as compared with TNFR1 KO 3 weekspost-infection, and further increased in both groups at 4–5 weeks." (PMID 26931771, 2016). "This is an agreement with our data showing decreased IL-1β production concomitant to reduced CXCL1 release during infection with the ST17 strain." (PMID 27527222, 2016). "In contrast, 6 h after infection, markedly higher serum levels of CXCL1, TNFα, and IL-6 were detected in mice infected with biofilm-released cells than in the biofilm cell-infected counterparts." (PMID 27729907, 2016).
infection (continued). "Pro-inflammatory cytokines (IFN-γ, IL-18, IL-6, TNF-α) and chemokines (CCL2, CCL5, CCL7, CXCL1, CXCL10) were found to be increased in sera of ZIKV-infected mice, indicating that infection causes systemic inflammation." (PMID 27163257, 2016). "The expression of proinflammatory cytokine IL-1β and the neutrophil chemokine CXCL1 were higher in 5b WT-infected mice throughout the course of infection." (PMID 27046446, 2016). "To determine if the defect in CXCL1 production was restricted to infection with viable bacteria, we challenged BMDM from WT (C57BL/6N) and Nlrp12−/− mice with a variety of toll-like receptor (TLR) agonists." (PMID 27779193, 2016). "Circulating neutrophils migrate to the infection site along a chemotactic gradient of potent chemoattractants, such as KC (CXCL1 or IL-8 in humans) and MIP-2 (CXCL2), produced at the infection site." (PMID 25974210, 2015). "To further explore the role of IL-17 in host defense against S. aureus intramammary infection, we focused on neutrophil-recruiting chemokines that are the key target genes of IL-17, such as CXCL1, CXCL2 and CXCL5." (PMID 26230498, 2015). "We found that both Cxcl1 and Cxcl2 were significantly induced following infection in both WT and Card9-/- mice whereas Cxcl5 was poorly induced." (PMID 26679537, 2015). "PMN recruitment to the sites of infection occurs in response to chemotactic stimuli, with CXCL1 and CXCL2 being among the most potent chemokines promoting PMN migration." (PMID 24651866, 2014). "For example, the gene expression levels of the cytokines Cxcl1, Cxcl2, Cxcl5 and Cxcl17 was in agreement with the recruitment of neutrophils and DCs towards the site of infection." (PMID 25137043, 2014). "As a consequence of the low CXCL-1 levels, neutrophilic recruitment to the site of infection was decreased after 24 hours." (PMID 25033194, 2014). "Consistent with our protein data, markedly decreased mRNA-levels of Cxcl-1 and Il-17 were observed as early as 12 hours post infection." (PMID 25033194, 2014). "Considering that transgenic expression of CXCL1 during the course of infection improved fungal burden and survival during infection with A. fumigatus, understanding the exact mechanism for HIF1α regulation of CXCL1 is of great importance." (PMID 25255025, 2014). "mCLCA3-deficiency was associated with decreased protein-levels of CXCL-1 and IL-17 in the BALF compared to wild-type mice 24 hours post infection." (PMID 25033194, 2014). "In B6 mice, three genes, Cxcl2 and the IFN-inducible gene Oasl2 (in myeloid cells) and Cxcl1 (in fibroblasts), tended to peak in expression at Day 7 post-infection." (PMID 24967703, 2014). "The role of miR-146a in regulating NF-κB activation was consistent with the observed defect in downregulation of NF-κB-dependent cytokines and chemokines IL-1β, IL-6, Cxcl1 and Cxcl2, in B6 miR-146a−/− mice at 4 weeks post-infection." (PMID 24967703, 2014). "Src kinase activity was also increased in caveolin-1 rich endosomal fractions after infection, and Src phosphorylation and CXCL1 induction were both decreased in caveolin-1-/- mice corneas compared to wild type mice." (PMID 24147000, 2013). "There was very significant inhibition of CXCL1 levels in BALF in OmCI treated mice 3 days after infection." (PMID 23696894, 2013). "Levels of IL-6 and CXCL-1 were higher in BAL of 5-LO−/− mice 72 h after infection compared with the same period in WT mice." (PMID 23991239, 2013). "Initial examination of raw cytokine/chemokine values revealed similar CXCL1 and IL-17 expression in both models (respectively) throughout the course of infection despite the dramatic differences in total bacterial burdens." (PMID 24386336, 2013). "The infection also activates the transcription of Cxcl1, Cxcl2 that regulate the influx of PMNs, Cxcl3 that controls migration of monocytes, Cxcl9 the Th1-attracting protein and the interferon-γ - inducible protein-10 (IP-10/Ccxl10)." (PMID 24148319, 2013).